ABCA1 (ATP binding cassette subfamily A member 1)
Description:
Catalyzes the translocation of specific phospholipids from the cytoplasmic to the extracellular/lumenal leaflet of membrane coupled to the hydrolysis of ATP. Thereby, participates in phospholipid transfer to apolipoproteins to form nascent high density lipoproteins/HDLs. Transports preferentially phosphatidylcholine over phosphatidylserine. May play a similar role in the efflux of intracellular cholesterol to apolipoproteins and the formation of nascent high density lipoproteins/HDLs. Translocates phospholipids from the outer face of the plasma membrane and forces it through its gateway and annulus into an elongated hydrophobic tunnel in its extracellular domain.
Synonyms: ABC-1; ABC1; CERP; TGD; HDLCQTL13; HDLDT1; HPALP1
Tractability: Small molecule: an approved drug acts on it; a structure with a bound ligand is known; it belongs to a druggable protein family. Antibody: UniProt places it where antibodies can reach, with high confidence; its Gene Ontology location is reachable by antibodies, with high confidence; UniProt predicts a signal peptide or a membrane-spanning region; the Human Protein Atlas places it where antibodies can reach. PROTAC: its protein half-life has been measured.
Target class: ATP-binding cassette; Transporter; ABCA subfamily; Primary active transporter
Gene: Protein-coding gene on chromosome 9 (104,781,006 to 104,928,155, reverse strand). Ensembl gene ENSG00000165029.
Subcellular location: Cell membrane; Endosome
Subcellular location (Human Protein Atlas): Plasma membrane; Golgi apparatus
Pathways (Reactome):
Disease: Defective ABCA1 causes TGD
Metabolism: PPARA activates gene expression
Signal Transduction: NR1H3 & NR1H2 regulate gene expression linked to cholesterol transport and efflux
Transport of small molecules: HDL assembly
Gene Ontology:
Molecular function: apolipoprotein A-I binding; apolipoprotein A-I receptor activity; apolipoprotein binding; ATP binding; ATPase binding; ATPase-coupled intramembrane lipid transporter activity; cholesterol transfer activity; floppase activity; phosphatidylcholine binding; phosphatidylcholine floppase activity; phosphatidylserine floppase activity; phospholipid transfer activity; protein binding; signaling receptor binding; small GTPase binding; sphingolipid floppase activity; syntaxin binding; ATPase-coupled transmembrane transporter activity; cholesterol binding; protein transmembrane transporter activity; ABC-type transporter activity; ATP hydrolysis activity; high-density lipoprotein particle binding
Biological process: adenylate cyclase-activating G protein-coupled receptor signaling pathway; cholesterol efflux; cholesterol homeostasis; cholesterol metabolic process; endosomal transport; G protein-coupled receptor signaling pathway; high-density lipoprotein particle assembly; intracellular cholesterol transport; lysosome organization; phospholipid efflux; phospholipid homeostasis; phospholipid translocation; platelet dense granule organization; protein secretion; regulation of Cdc42 protein signal transduction; response to laminar fluid shear stress; reverse cholesterol transport; signal release; cellular response to low-density lipoprotein particle stimulus; export across plasma membrane; negative regulation of cholesterol storage; negative regulation of macrophage derived foam cell differentiation; positive regulation of high-density lipoprotein particle assembly; protein transmembrane transport; regulation of high-density lipoprotein particle assembly; and 17 more
Cellular component: endocytic vesicle; endosome; intracellular vesicle; membrane raft; perinuclear region of cytoplasm; phagocytic vesicle; plasma membrane; endoplasmic reticulum membrane; basolateral plasma membrane; cell surface; external side of plasma membrane; Golgi apparatus; membrane
Genetic constraint (gnomAD): Loss-of-function variants: 130 observed, 267.32 expected, observed/expected ratio (o/e) 0.49, 90% interval 0.42 to 0.56. The upper end of that interval is the gene's LOEUF score, 0.56, which puts it in group 2 of 6, group 1 being the genes least tolerant of losing a copy. Missense variants: 2,446 observed, 2,899.5 expected, observed/expected ratio (o/e) 0.84, 90% interval 0.81 to 0.87. Synonymous variants: 1,018 observed, 1,100.3 expected, observed/expected ratio (o/e) 0.93, 90% interval 0.88 to 0.97.
Homologues: Orthologues: macaque ABCA1 (98% identical), chimpanzee ABCA1 (98% identical), rabbit ABCA1 (97% identical), mouse Abca1 (95% identical), pig ABCA1 (95% identical), dog ABCA1 (95% identical), rat Abca1 (93% identical), guinea pig ABCA1 (92% identical), tropical clawed frog abca1 (81% identical), zebrafish abca1a (74% identical), Caenorhabditis elegans abt-2 (28% identical), Drosophila melanogaster CG8908 (19% identical), and 3 more. Paralogues in human: ABCA4 (50% identical), ABCA7 (50% identical), ABCA2 (42% identical), ABCA12 (32% identical), ABCA13 (32% identical), ABCA3 (28% identical), ABCA5 (20% identical), ABCA9 (19% identical), ABCA6 (19% identical), ABCA8 (19% identical), ABCA10 (18% identical).
Diseases named in the same sentence as ABCA1 in open-access papers:
ABCA1 is named in the same sentence as 328 diseases in open-access papers, as found by Europe PMC text mining. Sharing a sentence is not in itself a finding about the gene and the disease. The quoted sentences say what the papers report.
atherosclerosis (451 papers, 2005 to 2026). A disease characterized by the build-up of fatty material and calcium deposition in the arterial wall resulting in partial or complete occlusion of the arterial lumen. "ABCA1 is a cellular cholesterol transporter; however, when bound by Nef, the expression of ABCA1 is downregulated, leading to lipid accumulation in macrophages and their conversion to foam cells, a hallmark of atherosclerosis." (PMID 40244289, 2025). "The bone marrow transplantation (BMT) of myeloid cell-specific ABCA1/G1-deficient cells induced monocytosis and neutrophilia and accelerated atherosclerosis, with an enlarged necrotic core area observed." (PMID 40305368, 2025). "Recent studies have shown that atherosclerosis is accelerated and foam cell production is increased when macrophage ABCA1/G1 is deficient." (PMID 40867523, 2025). "For example, MYOCD deficiency exacerbates atherosclerosis by downregulating ABCA1‐dependent cholesterol efflux in VSMCs." (PMID 41031220, 2025). "In atherosclerosis, defective ABCA1-mediated cholesterol efflux in macrophages—caused by loss-of-function mutations like p.Glu1282Lys—impairs lipid droplet clearance and promotes NLRP3 inflammasome activation via mitochondrial ROS accumulation." (PMID 40943400, 2025). "Meanwhile, combined Abca1 and Abcg1 deficiency promotes fat cell accumulation and accelerates the development of atherosclerosis in mice." (PMID 39857239, 2024). "Genetic polymorphisms within ABCA1 or ABCG1 have been associated with susceptibility to atherosclerosis." (PMID 38474781, 2024). "Variations in ABCA1 can cause Tangier disease, characterized by impaired lipid efflux from macrophages leading to early atherosclerosis and low HDL levels." (PMID 39238930, 2024). "Previous studies have consistently reported that hematopoietic deficiency of ABCA1 and SR-BI promoted skewed myelopoiesis and accelerated atherosclerosis." (PMID 36866528, 2023). "In humans, ABCA1 has been linked with atherosclerosis and ischemic heart disease, which is notable given that the Tsimane exhibit the lowest levels of coronary artery calcification reported for any population." (PMID 36574663, 2023). "CircRNA_ABCA1 expression was increased in aortic vessels of HFD-induced apoE-/- mice and H2O2-induced mouse aortic endothelial cells (MAECs) injury model, suggesting that circRNA_ABCA1 is a potential diagnostic biomarker for atherosclerosis." (PMID 37324939, 2023). "The findings show that the molecular mechanisms of fucoidan in underlying atherosclerosis reduce lipid accumulation and promote cholesterol efflux via activation of ABCA1 through LXR-α in THP1 macrophage-derived foam cells." (PMID 38001931, 2023). "ABCA1 deficiency in macrophages has been reported to increase inflammation and accelerate atherosclerosis in mice." (PMID 37322486, 2023). "Among the different processes in which miR-199a-5p participate, several targets are implicated in atherosclerosis including ABCA1, ABCG1, Cav-1, HIF1A, CD38, NCOR1, and SIRT1 in human and mouse." (PMID 36407436, 2022). "We summarized the ABCA1 transcription regulation mechanism, mutations, post-translational modifications, and their roles in the development of dyslipidemia, atherosclerosis, ischemia/reperfusion, myocardial infarction, and coronary heart disease." (PMID 35743794, 2022). "In human and animal models, ABCA1 mutations are positively correlated with aortic intima thickness and reduce macrophage cholesterol efflux and promote atherosclerosis." (PMID 36498944, 2022).
atherosclerosis (continued). "The excess cholesterol in macrophages can also be excreted by the ATP-binding cassette subfamily A member 1 (ABCA1) or subfamily G member 1 (ABCG1) which prevents the formation of foam cells thereby reducing the risk of atherosclerosis and CVD." (PMID 36159325, 2022). "In summary, the present study has demonstrated a protective role for asprosin in macrophage lipid accumulation and atherosclerosis development and revealed a novel mechanism underlying the modulation of ABCA1 and ABCG1 expression." (PMID 35902881, 2022). "Mutations of the ATP binding cassette transporter A1 (ABCA1), a transmembrane protein involved in the intracellular cholesterol efflux to lipid-poor apolipoprotein A-I, leads to premature atherosclerosis." (PMID 35563387, 2022). "Previous studies have identified that Nef-mediated inactivation of ABCA1 leads to cholesterol accumulation and augmentation of lipid raft abundance, thereby increasing the risk of atherosclerosis." (PMID 35743794, 2022). "Nevertheless, one particular characteristic should be stressed in relation to other studies on ABCA1 deficiency in vivo in the context of atherosclerosis." (PMID 36077004, 2022). "The-565C > T polymorphism in the ABCA1 gene promoter region was associated with not only changes in ABCA1 expression but also atherosclerosis severity." (PMID 35743794, 2022). "A prominent role for ABCA1 has already been described for atherosclerosis, where ABCA1 deficiency in macrophages that drive foam cell formation leads to the formation of atherosclerotic plaques." (PMID 35328615, 2022). "The miR-33-5p/ABCA1/CS axis plays pivotal roles in lipid metabolism and the underlying mechanisms of lipid metabolism disorders such as atherosclerosis and CVDs." (PMID 34517822, 2021). "ABCA1 played a pivotal role in the process of reverse cholesterol transport since the loss-function mutation of this gene caused severe early atherosclerosis (Tangier disease)." (PMID 34838043, 2021). "Mutations in ABCA1 cause Tangier disease characterized by a severe accumulation of cholesterol in macrophages responsible of prevalent atherosclerosis and premature CVD." (PMID 34360839, 2021). "In summary, the present study has demonstrated a novel role of macrophage CTRP12 in inhibiting the development of atherosclerosis and uncovered a novel mechanism underlying the regulation of ABCA1 and ABCG1." (PMID 33692340, 2021). "We also demonstrated that ABCA1 mRNA levels in EAT were reduced in CAD patients with concomitant carotid artery disease or peripheral artery disease, demonstrating a possible association of ABCA1 expression in EAT with severe multifocal atherosclerosis." (PMID 34837967, 2021). "It was shown that the inactivation of macrophage ABCA1 promotes increased atherosclerosis in ApoE-deficient mice." (PMID 34759279, 2021). "Taking into account the significance of metabolic syndrome and overweight in atherosclerosis, it was shown that obesity and insulin resistance are associated with lower ABCA1 expression in visceral adipose tissue." (PMID 34201488, 2021). "We previously reported that ERK1/2 inhibition synergizes liver X receptor (LXR)-reduced atherosclerosis in apoE deficient (apoE-/-) mice by enhancing reverse cholesterol transport and ATP-binding cassette transporter A1 (ABCA1) expression." (PMID 33391525, 2021). "Most studies exploring the role and function of ABCA1 have been conducted in cholesterol associated disease states such as atherosclerosis." (PMID 32977800, 2020). "Conditions of severe HDL deficiency and increased atherosclerosis have been described in some studies when the ABCA1 transporter is dysfunctional, including both in mice from which ABCA1 is ablated in the liver as well as in patients with Tangier disease." (PMID 30679232, 2019). "A molecular defect in the ABCA1 gene is the cause of Tangier disease, which leads to premature atherosclerosis, proteinuria, and HDL deficiency." (PMID 29681863, 2018).
atherosclerosis (continued). "Downregulation of ABCG1 and ABCA1 has been associated with reduced cholesterol efflux and has been shown to increase the risk of atherosclerosis." (PMID 29643945, 2018). "ABCA1 has emerged as the major cellular cholesterol efflux transporter, which has been implicated in several diseases like atherosclerosis, obesity and cancer." (PMID 29464044, 2018). "ABCA-1 contributes to the major amount of cholesterol exported from cholesterol-loaded macrophages and mutations in Abca1 gene cause atherosclerosis." (PMID 29867549, 2018). "This increases ABCA1 gene expression and causing greater macrophage cholesterol efflux, perhaps limiting foam cell formation to confer atherosclerosis protection." (PMID 27734214, 2017). "Studies revealed that LD-associated proteins ACAT1 and ABCA1 regulating cholesterol esterification play crucial roles in atherosclerosis." (PMID 28662670, 2017). "The ABCA1 gene (9q31.1) encoding the ATP-binding cassette transporter A1, plays a vital role in the pathogenesis of atherosclerosis and visual loss." (PMID 28915626, 2017). "In our in vivo study, EZH2 promoted the development of atherosclerosis in aortas of apoE−/− mice, which was associated with the higher DNA methylation level on ABCA1 promoter." (PMID 27295295, 2016). "ABCA1, atherosclerosis and endothelial cell homeostasis are associated with epigenetic changes in vitro and in vivo as described in experimental animal models and humans." (PMID 27295295, 2016). "The purpose of this study is to identify the molecular mechanism(s) underlying ABCA1 epigenetic modification and determine its potential impact on ABCA1 expression in macrophage-derived foam cell formation and atherosclerosis development." (PMID 27295295, 2016). "ABCA1 regulatory elements and variations in gene expression have also been associated with atherosclerosis." (PMID 25569858, 2015). "This supposition has been supported by the observation that the mutations in ABCA1 are associated with coronary artery calcification, a subclinical trait of atherosclerosis as well as CAD." (PMID 25958224, 2015). "Specifically, mutation of ABCA1 in humans has been shown to induce cholesterol accumulation in cells of the reticuloendothelial system, and increase susceptibility to atherosclerosis." (PMID 26317415, 2015). "Two-way ANOVA revealed independent effects on atherosclerosis for both leukocyte ABCA1 deficiency and SP-x (p<0.05)." (PMID 23133551, 2012). "Many studies have sought to associate ABCA1 genetic variants with the risk of HDL-C levels, atherosclerosis and coronary artery disease, and there is evidence that ABCA1 variation predicts ischemic heart disease in the general population." (PMID 23152888, 2012). "Mutation of ABCA1 induces intracellular cholesterol accumulation and increases susceptibility to atherosclerosis in humans and in animal models." (PMID 22984509, 2012). "Variations in ABCA1 gene and alteration in gene expression have been shown to affect the risk of atherosclerosis in animal models and invitro studies show that ABCA1 also modulates LDL oxidation in the artery wall cells." (PMID 17553166, 2007). "Importantly, T0901317 significantly stimulated atherosclerosis susceptibility, despite an associated increase in the macrophage gene expression levels of cholesterol efflux transporters ABCA1 and ABCG1." (PMID 38672446, 2024). "Ganoderma lucidum spore powder (GLSP) has been shown to mitigate the progression of atherosclerosis and the associated calcification of the aorta by enhancing the cholesterol transport processes mediated by ABCA1/G1, which are crucial for maintaining cellular lipid balance." (PMID 39524227, 2024).